CDKN2C (cyclin dependent kinase inhibitor 2C)
Description:
Interacts strongly with CDK6, weakly with CDK4. Inhibits cell growth and proliferation with a correlated dependence on endogenous retinoblastoma protein RB.
Synonyms: INK4C; p18; p18-INK4C
Tractability: PROTAC: ubiquitination databases record sites on it.
Gene: Protein-coding gene on chromosome 1 (50,960,745 to 50,974,634, forward strand). Ensembl gene ENSG00000123080.
Subcellular location (Human Protein Atlas): Cytosol; Nucleoplasm
Pathways (Reactome):
Cellular responses to stimuli: Oncogene Induced Senescence; Oxidative Stress Induced Senescence; Senescence-Associated Secretory Phenotype (SASP)
Cell Cycle: Cyclin D associated events in G1
Gene Ontology:
Molecular function: cyclin-dependent protein serine/threonine kinase inhibitor activity; protein binding; protein kinase binding
Biological process: negative regulation of cell growth; negative regulation of cell population proliferation; regulation of G1/S transition of mitotic cell cycle; oligodendrocyte differentiation; regulation of cell cycle
Cellular component: cytoplasm; nucleus; cytosol
Genetic constraint (gnomAD): Loss-of-function variants: 5 observed, 11.18 expected, observed/expected ratio (o/e) 0.45, 90% interval 0.23 to 0.94. The upper end of that interval is the gene's LOEUF score, 0.94, which puts it in group 3 of 6, group 1 being the genes least tolerant of losing a copy. Missense variants: 161 observed, 222.49 expected, observed/expected ratio (o/e) 0.72, 90% interval 0.64 to 0.82. Synonymous variants: 79 observed, 93.16 expected, observed/expected ratio (o/e) 0.85, 90% interval 0.71 to 1.02.
Cancer hallmarks: suppression of growth (promotes); escaping programmed cell death (suppresses)
Homologues: Orthologues: chimpanzee CDKN2C (100% identical), macaque CDKN2C (100% identical), rabbit CDKN2C (96% identical), dog CDKN2C (95% identical), pig CDKN2C (95% identical), guinea pig CDKN2C (93% identical), rat Cdkn2c (93% identical), mouse Cdkn2c (92% identical), tropical clawed frog cdkn2c (61% identical), zebrafish cdkn2c (51% identical). Paralogues in human: CDKN2D (43% identical), ANKRD39 (27% identical).
Diseases named in the same sentence as CDKN2C in open-access papers:
CDKN2C is named in the same sentence as 120 diseases in open-access papers, as found by Europe PMC text mining. Sharing a sentence is not in itself a finding about the gene and the disease. The quoted sentences say what the papers report.
glioma (11 papers, 2008 to 2025). A benign or malignant brain and spinal cord tumor that arises from glial cells (astrocytes, oligodendrocytes, ependymal cells). "Overall, the expression of LIN9, MCM8, CEP72, POLA1, DBF4, NDE1 and CDKN2C increase the prognostic risk for patients with glioma." (PMID 37349788, 2023). "Since the previous studies have explored the role of the signature genes METTL7B, SSTR2, OXTR, CDKN2C, and H19 in glioma, while TNFRSF11B has been poorly studied, we examined the functional impact of TNFRSF11B on LGG cell behavior." (PMID 37713112, 2024). "Regarding cellular functions, CDKN2C knockdown promoted R-2HG-treated glioma cell viability, suppressed apoptosis, and relieved cell cycle arrest." (PMID 38760850, 2024). "There was a strong positive correlation between E2F4 expression and the expression of MCM8, DBF4 and CDKN2C in both primary and recurrent glioma tissues, with the most prominent impact on patient prognosis being observed for MCM8." (PMID 37349788, 2023). "Our analysis revealed a significant positive correlation between E2F4 and MCM8, POLA1, DBF4, NDE1 or CDKN2C expression in primary gliomas." (PMID 37349788, 2023). "The correlation between E2F4 and LIN9, MCM8, CEP72, POLA1, DBF4, NDE1 or CDKN2C expression in glioma tissues was analyzed using CGGA." (PMID 37349788, 2023). "The CDKN2C (p18INK4C) locus at chromosome 1p showed focal deletions in nine gliomas, of which eight were primary glioblastomas and one was a grade II astrocytoma." (PMID 25797251, 2015). "Survey of a panel of 747 human cancer cell lines of 32 anatomical origins for genomic status of CDKN2A (p16INK4A and p14ARF) and CDKN2C revealed that codeletion of these two loci was observed predominantly in glioma tumor cell lines." (PMID 18394558, 2008). "Finally, we visualized the close association between CDCA3 and common glioma cell cycle checkpoint markers, including CDK6, CDK4, CDK2, CDK1, CDKN3, and CDKN2C, using circos plots." (PMID 38728485, 2024). "Mutations in genes, such as POLD1, CDKN2C, and HIST1H3B, are involved in the pathogenesis of various cancers, such as colorectal cancer, melanoma, and gliomas, but a mutation in these genes may be important for the progression of BRCA." (PMID 31311202, 2019). "The expression of MCM8, DBF4 and CDKN2C displayed a significant positive correlation with E2F4 expression in both primary and recurrent glioma tissues." (PMID 37349788, 2023). "In recurrent gliomas, E2F4 showed a significant positive correlation with the expression of MCM8, DBF4 and CDKN2C." (PMID 37349788, 2023). "The most commonly recurrent deletion events on chromosome 1p (ARID1A, CDKN2C, FUBP1) and chromosome 19q (CIC) were observed in gliomas of CYT-low cohort." (PMID 31428092, 2019). "In addition to the well-known and highly recurrent events, GTS defines and ranks many previously unrecognized CNAs, uncovers frequent codeletion of two related CKI genes, CDKN2C and CDKN2A, in human cancers, and implicates APAF1 and FBXW7 in glioma pathogenesis." (PMID 18394558, 2008).
myeloma (11 papers, 2006 to 2023). "Loss of CDKN2C, seen in 15% of myeloma cases, is associated with poorer OS." (PMID 35127532, 2021). "CDKN2C (p18) is deleted in myeloma clones with 1p−,63 associated with a poor prognosis." (PMID 28362441, 2017). "CDKN2C, located on chromosome 1p, encodes a CDK inhibitor and when deleted in myeloma cells results in increased proliferation." (PMID 35127532, 2021). "Homozygous deletion of CDKN2C has been found in myeloma, and copy number decrease of CDKN2C was significantly associated with a worse overall survival." (PMID 25502777, 2014). "Further investigation of CDKN2C and RB1 mutation, deletion and expression are required to more fully understand the interplay between disruption of these genes and cell cycle control in myeloma." (PMID 28234347, 2017). "Furthermore, frequent homozygous deletions of genes playing important role in myeloma biology such as TRAF3, BIRC1/BIRC2, RB1, or CDKN2C were observed." (PMID 24987674, 2014).
breast cancer (10 papers, 2008 to 2025). A primary or metastatic malignant neoplasm involving the breast. "Gain of the CCND1 and CDK4 and loss of the CDKN2A (p16) and CDKN2C (p18) genes are present in patients with luminal B breast cancer and poor prognosis of and negatively regulated by the cell cycle pathway." (PMID 33110086, 2020). "Given the tumor suppressor function of CDKN2C in breast cancer, a loss-of-function of CDKN2C may have driven tumor formation in AYA02; therefore, we selected CDK4/6 inhibitors as a potential drug (palbociclib and LY2835219)." (PMID 26925973, 2016). "Only KTR14, KRT16, CXCL9, and CFD in BRCA1 Ovarian Cancer and TSPAN7 and CDKN2C in BRCA2 ovarian cancers were highly upregulated, and KANK4, MFGE8, LINC00346, and SA100A1 in BRCA1 mutated breast cancer, and MAGEA4 in BRCA2 breast cancers." (PMID 40647506, 2025). "ER + breast cancer frequently demonstrates gain of CCND 1 (cyclin D1) and CDK4 and loss of CDKN2A (p16) and CDKN2C (p18)." (PMID 36229710, 2022).
melanoma (10 papers, 2007 to 2023). A malignant, usually aggressive tumor composed of atypical, neoplastic melanocytes. "Both hsa-miR-21-5p and hsa-miR-221-3p are onco-miRNAs, and hsa-miR-21-5p was found upregulated in melanoma tissues, and in vitro experiments have established its role in cell cycle regulation by targeting the cyclin-dependent kinase inhibitor 2C (CDKN2C)." (PMID 37387784, 2023). "In summary, this study demonstrated that miR‐21‐5p was up‐regulated in melanoma, which accelerates the malignant progression of melanoma by promoting cell proliferation and cell‐cycle G1/S transition through targeting CDKN2C." (PMID 32090490, 2020). "In our experiment, knockdown of CDKN2C imitated, whereas its overexpression attenuated, the effects of miR‐21‐5p on melanoma cell growth and cell‐cycle G1/S transition." (PMID 32090490, 2020). "Here, we found that CDKN2C 3′ UTR has a binding site with miR‐21‐5p, and confirmed that CDKN2C was a direct target of miR‐21‐5p in melanoma cells." (PMID 32090490, 2020). "miR‐21‐5p down‐regulates CDKN2C expression, thereby promoting G1/S transition and enhancing cell proliferation in melanoma." (PMID 32090490, 2020). "CDKN2C mRNA levels were notably down‐regulated in melanoma tissues in comparison with adjacent tissues." (PMID 32090490, 2020). "The main objective of this study was to reveal the regulatory role of miR‐21‐5p and CDKN2C in melanoma cell proliferation and cell‐cycle progression." (PMID 32090490, 2020). "The data further demonstrated that miR‐21‐5p promoted cell proliferation and cell‐cycle G1/S transition by directly down‐regulating CDKN2C in melanoma cells." (PMID 32090490, 2020). "To investigate whether CDKN2C was a downstream functional factor involved in miR‐21‐5p regulating cell proliferation and cell‐cycle G1/S transition in melanoma, we performed rescue experiments by cotransfecting miR‐21‐5p mimic and pcDNA‐CDKN2C into A375 cells." (PMID 32090490, 2020). "Furthermore, Spearman’s correlation analysis further demonstrated that the expression of miR‐21‐5p was inversely correlated with the CDKN2C mRNA levels in melanoma tissues (P = 0.0264)." (PMID 32090490, 2020). "Despite a negative regulatory role of CDKN2C in G0/G1 cell‐cycle progression, the functional role of CDKN2C in cell‐cycle regulation still remains unknown in melanoma." (PMID 32090490, 2020). "Our study may provide new evidence to elucidate the role of miR‐21‐5p and CDKN2C in melanoma progression." (PMID 32090490, 2020). "Overall, our studies demonstrate that miR‐21‐5p can promote the growth of melanoma cells by targeting CDKN2C, which may induce G0/G1 phase arrest of melanoma cells." (PMID 32090490, 2020). "Furthermore, miR‐21‐5p mimics resulted in a decrease in CDKN2C expression, and CDKN2C expression was observed to be inversely correlated with miR‐21‐5p expression in melanoma tissues." (PMID 32090490, 2020). "Our preliminary results suggest that the miR‐21‐5p/CDKN2C axis might be a potential therapy in future melanoma treatment." (PMID 32090490, 2020). "Furthermore, we further evaluated whether miR‐21‐5p regulates cell proliferation and cell cycle by directly targeting CDKN2C in melanoma cells." (PMID 32090490, 2020). "It has been shown that miR-21-5p is upregulated in melanoma, NSCLC, GC and promotes tumor proliferation and invasion by targeting CDKN2C/SET/TAF-Iα." (PMID 37308993, 2023). "Among the genes that were downregulated by silencing this deacetylase are those that have been positively correlated with melanoma aggressiveness (e.g., NCAPG, CDKN2C, GINS1, and DHFR are all downregulated in the SSW30 clone)." (PMID 31091806, 2019). "In human melanoma A375 cells, miR-21 promotes proliferation, migration, and suppresses apoptosis by inhibiting Sprouty 1 (SPRY1), programmed cell death 4 (PDCD4), PTEN and cyclin-dependent kinase inhibitor 2C (CDKN2C)." (PMID 32751207, 2020).
melanoma (continued). "While other genes (e.g. CDKN2C, CDKN2A, MITF, BAP1, PTEN, ERBB4, and FGFR2, etc.)are mutated with some frequency in melanoma, no common recurring mutations in these genes are observed or the function of observed mutations are unknown; therefore these genes were not included in our screen." (PMID 22536370, 2012).
prostate carcinoma (10 papers, 2010 to 2025). A carcinoma that arises from epithelial cells of the prostate gland. "In prostate cancer, E2F-related gene signatures encompassing CDKN2C can be used to stratify recurrence risk, with higher signature expression predicting worse recurrence-free survival, which is consistent with net pathway activation despite the nominal inhibitory role of CDKN2C." (PMID 41226058, 2025). "CDKN2C has previously been described as a candidate tumour suppressor gene, but it has been observed in many types of cancer, including leukaemia and prostate cancer, as well as malignant meningiomas and oligodendrogliomas." (PMID 39409884, 2024).
glioblastoma (9 papers, 2008 to 2025). The most malignant astrocytic tumor (WHO grade IV). "Moreover, CDKN2C is a well characterized tumor suppressor gene associated with many cancers and known to be deleted in Glioblastoma." (PMID 30059495, 2018). "The 624-mel cell line contained a mutated BRAF gene (Val600Glu), while both glioblastoma cell lines are characterized by a TERT promotor mutation and a CDKN2C deletion." (PMID 40955425, 2025). "It is reported that co-deletion of CDKN2A and CDKN2C confer Palbociclib-sensitivity in glioblastoma and soft tissue sarcoma, demonstrating that amplification of CDK4 benefits from the CDK4/6 inhibitor." (PMID 38369555, 2024). "It has been shown that CDKN2C expression is significantly increased in glioblastoma compared to non-neoplastic white matter." (PMID 39409884, 2024).
lung carcinoma (7 papers, 2016 to 2025). "Moreover, based on the 11 raw datasets with both SCLC and NSCLC samples (n = 1135), CDKN2C expression made it feasible to differentiate SCLC from NSCLC (sensitivity = 0.87, specificity = 0.94, AUC = 0.96), implying CDKN2C was a potential marker identifying the two subtypes of lung cancer." (PMID 35751045, 2022). "That is, the high expression of CDKN2C was mainly observed in head and neck cancers (GBM and HNSCC), lung cancers (SCLC, LUAD, and LUSC), and digestive system cancers outside the colorectum (CHOL, ESCA, LIHC, and STAD)." (PMID 35751045, 2022).
medulloblastoma (7 papers, 2014 to 2026). A malignant, invasive embryonal neoplasm arising from the cerebellum. "Loss of one copy of Dicer induced SHH medulloblastoma with a similar time of onset and penetrance in Dicerfloxed/+; Nestin-Cre+; Ptch1+/-; Cdkn2c+/- compared to Dicer+/+; Ptch1+/-; Cdkn2c+/- mice, 76.5% (39/51) versus 62% (31/50), respectively." (PMID 26091048, 2015). "Loss of one copy of Dicer accelerated medulloblastoma formation in Ptch1+/-, Cdkn2c+/- animals." (PMID 26091048, 2015). "SHH medulloblastoma arise from GNPs with aberrant SHH signaling upon deletion of one copy of the SHH receptor Patched (Ptch1+/-) alone or with one or two copies of Cdkn2c." (PMID 26091048, 2015). "In contrast, none of the 12 mice transplanted with GNPs purified from the cerebella of P7 miR-17∼92cKO; Ptch1+/−; Cdkn2c+/− mice and expressing Mycn developed medulloblastoma, 180 days post-implantation." (PMID 24928431, 2014).
gastric cancer (6 papers, 2018 to 2025). A primary or metastatic malignant neoplasm involving the stomach. "PRMT5 interacts with c-Myc and inhibits PTEN, CDKN2C (p18INK4C), CDKN1A (p21CIP1 or WAF1), CDKN1C (p57KIP2), and p63 gene expression to promote gastric cancer cell growth." (PMID 41154773, 2025). "In this study, we found that c-Myc could interact directly with PRMT5 to transcriptionally repress the expression of a cohort of genes, including PTEN, CDKN2C (p18INK4C), CDKN1A (p21CIP1/WAF1), CDKN1C (p57KIP2) and p63, to promote gastric cancer cell growth." (PMID 32292506, 2020).
pituitary adenomas (6 papers, 2012 to 2025). "Indeed, the CDKN2C gene, which could be a target of miR-664, has been demonstrated to be frequently lost in pituitary adenomas." (PMID 34298972, 2021). "In addition, we describe a novel variant in CDKN2C gene with uniparental disomy in tumour sample that was classified as uncertain significance in a patient with PHPT and a non-functional pituitary adenoma." (PMID 36334246, 2023). "Additionally, a novel variant of the CDKN2C gene with uniparental disomy was classified as VUS in a patient with PHPT and a non-functional pituitary adenoma." (PMID 37810884, 2023).
colorectal cancer (4 papers, 2012 to 2025). A primary or metastatic malignant neoplasm that affects the colon or rectum.
Hodgkins lymphoma (4 papers, 2012 to 2024). A heterogeneous group of malignant lymphoid neoplasms of B-cell origin characterized histologically by the presence of Hodgkin and Reed-Sternberg (HRS) cells in the vast majority of cases. "CDKN2C was previously reported to be inactivated by promoter hypermethylation in Reed-Sternberg cells in Hodgkin lymphomas, and the loss of CDKN2C showed negative correlation with the overall survival of the patients." (PMID 23049694, 2012).
lupus (4 papers, 2016 to 2021). "In the past decade, three lupus susceptibility genes, CDKN2c, CSF3R, and mutant Skint6, have been identified from the Sle2c1 locus of the NZM2410 strain." (PMID 34720750, 2021). "B6.Sle1.Sle2.Sle3 (B6.TC) lupus-prone mice carrying the NZB allele of Cdkn2c, encoding for the cyclin-dependent kinase inhibitor P18INK4, accumulate B-1a cells due to a higher rate of proliferative self-renewal." (PMID 27047495, 2016).
chordoma (3 papers, 2011 to 2023). Chordomas are rare malignant tumors arising from embryonic remnants of the notochord in axial skeleton. "Second, studies of genetic alterations in chordoma identified mutation or loss of the cell cycle regulator CDKN2A, which is of interest since we identified CDKN2C and CDKN3 as hits in a screen for proteins whose depletion enhances sensitivity to IGF-1R inhibition." (PMID 27200287, 2016). "The genetic alteration (deep deletion) frequency showed that 1/3rd of the chordoma samples have MTAP loss and CDKN2A, CDKN2B and CDKN2C loss; however, there is no loss in the folate pathway genes in the samples analyzed in personalized oncogenomics cBioPortal." (PMID 37147496, 2023).